ATP2B2 (ATPase plasma membrane Ca2+ transporting 2)
Description:
ATP-driven Ca(2+) ion pump involved in the maintenance of basal intracellular Ca(2+) levels in specialized cells of cerebellar circuit and vestibular and cochlear systems. Uses ATP as an energy source to transport cytosolic Ca(2+) ions across the plasma membrane to the extracellular compartment. Has fast activation and Ca(2+) clearance rate suited to control fast neuronal Ca(2+) dynamics. At parallel fiber to Purkinje neuron synapse, mediates presynaptic Ca(2+) efflux in response to climbing fiber-induced Ca(2+) rise. Provides for fast return of Ca(2+) concentrations back to their resting levels, ultimately contributing to long-term depression induction and motor learning (By similarity). Plays an essential role in hearing and balance. In cochlear hair cells, shuttles Ca(2+) ions from stereocilia to the endolymph and dissipates Ca(2+) transients generated by the opening of the mechanoelectrical transduction channels. Regulates Ca(2+) levels in the vestibular system, where it contributes to the formation of otoconia. In non-excitable cells, regulates Ca(2+) signaling through spatial control of Ca(2+) ions extrusion and dissipation of Ca(2+) transients generated by store-operated channels. In lactating mammary gland, allows for the high content of Ca(2+) ions in the milk (By similarity).
Synonyms: PMCA2; DFNA82; PMCA2a; PMCA2i
Tractability: Small molecule: it belongs to a druggable protein family. Antibody: UniProt places it where antibodies can reach, with high confidence; its Gene Ontology location is reachable by antibodies, with high confidence; UniProt predicts a signal peptide or a membrane-spanning region. PROTAC: ubiquitination databases record sites on it; its protein half-life has been measured.
Gene: Protein-coding gene on chromosome 3 (10,324,023 to 10,708,007, reverse strand). Ensembl gene ENSG00000157087.
Subcellular location: Cell membrane; Synapse; Apical cell membrane (Isoform WA); Basolateral cell membrane; Apical cell membrane (Isoform WB); Basolateral cell membrane (Isoform XB); Basolateral cell membrane (Isoform ZA); Basolateral cell membrane (Isoform ZB)
Pathways (Reactome):
Sensory Perception: Sensory processing of sound by inner hair cells of the cochlea; Sensory processing of sound by outer hair cells of the cochlea
Hemostasis: Reduction of cytosolic Ca++ levels
Muscle contraction: Ion homeostasis
Transport of small molecules: Ion transport by P-type ATPases
Gene Ontology:
Molecular function: P-type calcium transporter activity; P-type calcium transporter activity involved in regulation of postsynaptic cytosolic calcium ion concentration; protein binding; ATP binding; ATP hydrolysis activity; calcium-dependent ATPase activity; nucleotide binding
Biological process: calcium ion transport; neuron differentiation; regulation of cytosolic calcium ion concentration; sensory perception of sound; monoatomic ion transmembrane transport; regulation of cardiac conduction; calcium ion transmembrane transport; cochlea development; regulation of postsynaptic cytosolic calcium ion concentration
Cellular component: apical plasma membrane; basolateral plasma membrane; cytoplasm; extracellular exosome; GABA-ergic synapse; glutamatergic synapse; plasma membrane; dendritic spine membrane; postsynaptic density membrane; synapse; cilium; endoplasmic reticulum; membrane; neuronal cell body; photoreceptor ribbon synapse; presynaptic membrane
Genetic constraint (gnomAD): Loss-of-function variants: 15 observed, 121.6 expected, observed/expected ratio (o/e) 0.12, 90% interval 0.082 to 0.19. The upper end of that interval is the gene's LOEUF score, 0.19, which puts it in group 1 of 6, group 1 being the genes least tolerant of losing a copy. Missense variants: 1,045 observed, 1,772.2 expected, observed/expected ratio (o/e) 0.59, 90% interval 0.56 to 0.62. Synonymous variants: 694 observed, 724.6 expected, observed/expected ratio (o/e) 0.96, 90% interval 0.9 to 1.02.
Gene-disease validity (ClinGen):
ClinGen rates the evidence that ATP2B2 causes each of these diseases.
autosomal dominant nonsyndromic hearing loss (autosomal dominant): Definitive. Autosomal dominant form of nonsyndromic deafness.
Homologues: Orthologues: chimpanzee ATP2B2 (99% identical), macaque ATP2B2 (99% identical), dog ATP2B2 (99% identical), pig ATP2B2 (99% identical), mouse Atp2b2 (98% identical), guinea pig ATP2B2 (97% identical), rat Atp2b2 (96% identical), zebrafish atp2b2 (85% identical), rabbit ATP2B2 (73% identical), Caenorhabditis elegans mca-3 (58% identical), Caenorhabditis elegans mca-2 (54% identical), zebrafish si:dkey-28b4.8 (25% identical), and 11 more. Paralogues in human: ATP2B3 (82% identical), ATP2B1 (79% identical), ATP2B4 (73% identical), ATP1A1 (24% identical), ATP1A2 (24% identical), ATP2A2 (24% identical), ATP1A3 (24% identical), ATP2A1 (24% identical), ATP12A (23% identical), ATP2A3 (23% identical), ATP1A4 (23% identical), ATP4A (23% identical), and 9 more.